PLN (phospholamban)
Diseases named in the same sentence as PLN in open-access papers (continued):
Sharing a sentence is not in itself a finding about the gene and the disease.
cardiomyopathy (continued). "We demonstrated that the newly generated PLN-R14del mouse model closely mimics the human phenotype of PLN-R14del-related cardiomyopathy." (PMID 32555305, 2020). "We observed a delayed onset of cardiomyopathy in PLN-R14Δ/+ mice, including impaired cardiac contractile function after 18 months of age, increased myocardial fibrosis, and the presence of PLN protein aggregation." (PMID 32555305, 2020). "This is the first report of descendants from the original Dutch founder population of patients with phospholamban R14del cardiomyopathy." (PMID 30806910, 2019). "Transgenic mice, overexpressing the PLN-R14Del protein, recapitulated the human cardiomyopathy and resulted in premature death." (PMID 28102477, 2017). "In humans mutations in the PLN gene, encoding phospholamban - a regulator of sarcoplasmic reticulum calcium ATPase (SERCA), cause cardiomyopathy with prevalence depending on the population." (PMID 25928149, 2015). "Transgenic mice overexpressing the mutant PLN-R14del showed extensive myocardial fibrosis, myocyte disarray, ventricular dilation and premature death, recapitulating human cardiomyopathy." (PMID 24732829, 2014). "In this narrative review, we focus on cardiomyopathy-associated genotypes consistently linked to high arrhythmic risk-LMNA, truncating variants in FLNC, RBM20, PLN p.Arg14del, and desmosomal genes-and examine their molecular mechanisms, phenotypic trajectories, and arrhythmogenic profiles." (PMID 42074488, 2026). "LMS with non-TTN genetic cardiomyopathies, consisting of mutations in PLN and LMNA genes, exhibited elevated post pause potentiation and efficient contractile force at low pacing frequency." (PMID 40799359, 2025). "To investigate whether EPAS1, BNIP3L, and SOD2 induction is a common feature of cardiomyopathy, we also assessed the levels in additional patient hearts with mutations in PKP2 and phospholamban (PLN), associated with ACM and DCM." (PMID 40034852, 2025). "SERCA2 super-inhibition by PLN-R14del was described as a hypothesis for PLN-R14del cardiomyopathy, focusing on SR function." (PMID 40791987, 2025). "Although PLN-R14del cardiomyopathy was originally described to be a disease driven by reduced SR-calcium uptake, more recent data show enhanced SR-calcium uptake in a PLN-R14del mouse model and in human induced pluripotent stem cells-derived cardiomyocytes (hiPSC-CM)." (PMID 38334971, 2024). "Together with the observation that DWORF overexpression delays disease development in homozygous PLN-R14del mice, these findings prompted us to investigate whether a reduction in DWORF could accelerate or exacerbate PLN-R14del cardiomyopathy." (PMID 38334971, 2024). "ACM-causing mutations have also been identified in genes outside the desmosome, including phospholamban (PLN), filamin C (FLNC), desmin (DES), titin (TTN), and lamin A/C (LMNA), which are linked with other cardiomyopathies, including DCM and neuromuscular cardiomyopathies." (PMID 38610600, 2024). "Overall, these results suggest that intercalated disk architecture may be altered at an early stage of R14Δ-PLN cardiomyopathy." (PMID 39446877, 2024). "However, because of the unique PLN-R14del cardiomyopathy disease mechanism, we cannot exclude detrimental effects of low DWORF levels in other types of cardiac disease." (PMID 38334971, 2024). "This competition may involve not only SERCA but also other interacting proteins and requires more elaborate future investigations, which could provide intriguing new leads for the cardioprotective mechanisms of DWORF in PLN-R14del cardiomyopathy." (PMID 38334971, 2024). "For example, frequent exercise is associated with an earlier onset of ACM in desmosomal gene variant carriers but does not influence PLN-R14del cardiomyopathy development." (PMID 38334971, 2024). "Together, these results demonstrate that absence of DWORF does not accelerate or exacerbate PLN-R14del cardiomyopathy in mice harboring the pathogenic R14del allele." (PMID 38334971, 2024).
cardiomyopathy (continued). "Until now, there is no specific treatment available for patients with PLN R14del-associated cardiomyopathy." (PMID 35699837, 2022). "To investigate whether administration of a PLN-ASO could halt or even reverse established PLN-R14del cardiomyopathy, we aimed to initiate treatment when PLN-R14 Δ/Δ mice had considerable HF." (PMID 35269571, 2022). "Thus, the effect of PLN inhibition in a clinically relevant setting of established cardiomyopathy remains yet unexplored." (PMID 35269571, 2022). "We identified common variants within genes implicated in cardiomyopathies (e.g. BAG3, FHOD3, PLN), suggesting sarcomere homeostasis during mechanical stress may affect diastolic function in both health and disease." (PMID 35479509, 2022). "iPHORECAST is a multicentre, prospective randomised controlled trial designed to address whether pre-emptive treatment of PLN p.Arg14del carriers with eplerenone can prevent or delay the onset of cardiomyopathy." (PMID 34143416, 2022). "In conclusion, these findings indicate that PLN-ASO therapy may have beneficial outcomes in PLN-R14del cardiomyopathy when administered after disease onset." (PMID 35269571, 2022). "We reasoned that ASO induced reductions of PLN protein expression has the potential to prevent disease development and progression, thereby representing a possible precision medicine approach to treat PLN R14del induced cardiomyopathy." (PMID 34462437, 2021). "The more specific PLN-ASO therapy, in contrast, could prevent all characteristic signs of PLN R14del cardiomyopathy: PLN protein aggregation, severe cardiac fibrosis, cardiac dilatation, impaired contractility, and abnormal ECG readings." (PMID 34462437, 2021). "The resulting reductions in PLN protein expression prevented or reversed cardiac dysfunction in three different rodent models of HF and cardiomyopathy, and significantly increased lifespan in a model of hereditary PLN R14del cardiomyopathy." (PMID 34462437, 2021). "This pharmacological investigation also aims to test the hypothesis that such SERCA2a activators may serve as a mechanism-targeted treatment of PLN p.Arg14del cardiomyopathy." (PMID 34948294, 2021). "While beneficial effects resulted from PLN ablation in mice, the absence of PLN protein in patients was associated with severe cardiomyopathy." (PMID 33998164, 2021). "Heterozygous PLN-R14del mice demonstrated increased susceptibility to ex vivo induced arrhythmias, and cardiomyopathy at 18 months of age, which was not accelerated by isoproterenol infusion." (PMID 32555305, 2020). "Besides the DCM phenotype, the development of VAs is another key feature of PLN-R14del cardiomyopathy in human patients." (PMID 32555305, 2020). "Thus, the phospholamban R14del cardiomyopathy portends a much worse prognosis compared to those with ‘typical’ ARVC or DCM, potentially influencing decision-making surrounding advanced heart failure management." (PMID 30806910, 2019). "Further studies would be required to understand whether the delayed manifestation of the phospholamban phenotype may be the result of genetic heterogeneity, when most studies suggest a Mendelian inheritance of the phospholamban cardiomyopathy phenotype." (PMID 30806910, 2019). "We have demonstrated with the examples of Titin, FHL1, MLP/Csrp3, Filamin C and Phospholamban discussed here, that there are disease genes for cardiomyopathies beyond the “classical” genes coding for proteins with exclusively structural roles in the sarcomere or the cytoskeleton." (PMID 29119312, 2017). "Recent reports of human cases of CNM coexisting with cardiomyopathy further highlight the importance of assessing the existence of CNM in skeletal muscles from patients with cardiomyopathy arising from PLN mutations." (PMID 26035394, 2015). "The phenotype of two c.9_10insA:(p.Val4Serfs*15) variant carriers suggests that heterozygous truncating PLN mutations have low penetrance or do not cause cardiomyopathy at all." (PMID 25928149, 2015).
cardiomyopathy (continued). "Here the authors show that cardiomyocytes derived from induced pluripotent stem cells of a cardiomyopathy patient with mutant PLN exhibit functional defects consistent with the disease, and that this mutation can be functionally corrected by genome editing and gene therapy." (PMID 25923014, 2015). "Detailed histologic analysis of the pattern of fibrosis and fatty changes in PLN mutation associated cardiomyopathies has not been extensively studied and to the best of our knowledge has not been performed on transverse heart slices." (PMID 24732829, 2014). "Genetic ablation of phospholamban results in augmented SERCA function and has been shown to augment cardiac function in muscle specific LIM protein deficient mice, a well characterized model of mammalian cardiomyopathy." (PMID 24098595, 2013). "Worldwide, several PLN variants have strong association with variable cardiac phenotypes ranging from dilated cardiomyopathy to hypertrophic and even arrhythmogenic cardiomyopathy (ACM), but the causative defects leading to cardiomyopathies remain incompletely elucidated." (PMID 38392255, 2024). "In addition, altered myofilament activity is an early characteristic of R14del-PLN mutant hearts and the positive inotropic drug omecamtiv mecarbil may be beneficial in treating R14del-PLN cardiomyopathy." (PMID 36768995, 2023). "Since patients often already have HF at primary presentation, and asymptomatic carriers are only treated after disease onset, we herein aimed to determine whether PLN-ASO administration has beneficial effects in a clinically relevant stage of advanced PLN-R14del cardiomyopathy." (PMID 35269571, 2022). "Thus, we present insight into the pathophysiology of Phospholamban p.Arg14del cardiomyopathy." (PMID 34887420, 2021). "In the analyzed heart slices from PLN p.Arg14del mutation carriers with nonischemic cardiomyopathy we found an overlap in distribution pattern between patients with DCM and AC and a significant higher percentage of adipose tissue in AC compared to control hearts (p = 0.028)." (PMID 24732829, 2014). "Various gene therapies are currently in development, including those aimed at myosin-binding protein C3 (MYBPC3)-related cardiomyopathy (NCT05836259) and the use of antisense oligonucleotides for PLN-R14del cardiomyopathy." (PMID 39674807, 2025). "In this study, we showed a dose dependent treatment effect with PLN-ASO on cardiac remodelling and survival in a murine PLN-R14del cardiomyopathy model." (PMID 40905134, 2025). "Validation of PLN inhibition after PLN-ASO administration was limited by the different ages and stages of cardiomyopathy of the experimental groups." (PMID 35269571, 2022). "We demonstrated that PLN-ASO administration lowers PLN levels, and halts disease progression in PLN-R14 Δ/Δ mice with progressive cardiomyopathy." (PMID 35269571, 2022). "Overall, lead variants at 9 of the 61 GWS loci were located nearest to known cardiomyopathy genes (ACTN2, ALPK3, BAG3, FLNC, PLN, TTN), representing significant enrichment (hypergeometric p = 6.01 × 10−11)." (PMID 36376295, 2022). "Mutations in PLN cause cardiomyopathy in a distinct way, as they may not directly influence the structural or functional characteristics of cardiomyocytes, but disrupt the calcium homeostasis inside cardiomyocytes and interrupt the rhythm of myocardial contraction." (PMID 33020536, 2020). "This can be illustrated by the effect of oxidative stress on the phospholamban and SERCA that may lead to impairing diastole or systole (cardiomyopathy and failure)." (PMID 40437590, 2025). "Together, we demonstrate that deletion of DWORF does not cause cardiac dysfunction in aging mice and does not accelerate or exacerbate PLN-R14del cardiomyopathy in R14Δ/+ mice." (PMID 38334971, 2024).
cardiomyopathy (continued). "In this study, we demonstrate that deletion of DWORF does not cause age-dependent cardiac dysfunction and does not enhance or accelerate PLN-R14del cardiomyopathy in a heterozygous mouse model of this disease." (PMID 38334971, 2024). "The analysis of p62-positive aggregates in the myocardium showed a high prevalence of diffused p62-positive aggregates in phospholamban (PNL) and desmin-related (DRC) cardiomyopathy patients, confirming earlier findings in a mouse model of DRC desmin mutant and impaired lysosomal function." (PMID 37176163, 2023). "As there is no specific therapy for PLN-R14del-related cardiomyopathy, current HF guidelines, which recommend treatment with angiotensin-converting enzyme (ACE) inhibitors, beta-blockers and MRAs or a combination, are applied for treatment." (PMID 32555305, 2020). "Two genes (ACTN2 and PLN) best fit an intrinsic (primary) cardiomyopathy phenotype given there were no extracardiac features reported." (PMID 30681346, 2019). "In this review we discuss selected examples of cardiomyopathy genes (TTN, FHL1, CSRP3, FLNC and PLN) which, based on their known biological functions and the (limited) functional work on the disease-causing pathogenic variants, have been shown to have important signalling functions in the heart." (PMID 29119312, 2017). "In specific, DWORF overexpression attenuated PLN-R14del cardiomyopathy in mice via inhibition of abnormal PLN S/ER-clustering, since DWORF could not further enhance the already accelerated calcium reuptake in PLN-R14del mice." (PMID 38334971, 2024). "Additional cluster 3 proteins categorized to cardiomyopathy and sarcomeric proteins exposed to constant mechanical stress, including Desmin (DES), dystrophin muscular dystrophy (DMD); myosin binding protein C, cardiac (MYBPC3); myosin light polypeptide 2 (MYL2); Titin (TTN) and phospholamban (PLN)." (PMID 36681760, 2023). "Advances in genetic characterization of cardiomyopathies have identified some desmosomal genes such as DSP and non-desmosomal genes such as Phospholamban, Filamin-C, and Transmembrane Protein 43, that are often associated with biventricular or LV-dominant subforms." (PMID 40021092, 2025).
dilated cardiomyopathy (57 papers, 2009 to 2026). Cardiomyopathy which is characterized by dilation and contractile dysfunction of the left and right ventricles. "Pathogenic variants in the PLN gene are known to impair cardiac muscle function, increasing the risk of arrhythmogenic and dilated cardiomyopathy, and ventricular arrhythmias." (PMID 41287789, 2025). "Previously published studies reported PLN variants as a rare cause of hypertrophic or dilated cardiomyopathies, with the exception of p.Arg14del variant which was found with higher frequency among patients with DCM and ACM." (PMID 38392255, 2024). "Heterozygosity for the p.Leu39Ter variant in the PLN gene has also been identified in two male patients with dilated cardiomyopathy." (PMID 39273332, 2024). "Individuals with the pathogenic c.40_42del; p.(Arg14del) variant in the PLN gene are frequently diagnosed with ARVC or dilated cardiomyopathy (DCM)." (PMID 37474840, 2023). "Several mutations have been identified in the PLN gene causing cardiac disease associated with arrhythmogenic and dilated cardiomyopathy." (PMID 37408239, 2023). "Several human mutations have been identified in the PLN gene causing a cardiac disease associated with variable phenotypes including arrhythmogenic and dilated cardiomyopathy." (PMID 37408239, 2023). "The same NHEJ pathway was induced by CRISPR/Cas9 genome editing in a humanized mouse model of arrhythmogenic dilated cardiomyopathy caused by a truncating variant in phospholamban (PLN)." (PMID 37408197, 2023). "Phospholamban (PLN) has been linked with the pathogenesis of both AC and dilated cardiomyopathy (DCM) in p.(Arg14del) carriers." (PMID 37509658, 2023). "The PLN-R14del mutation was first discovered in a large Greek family with clinical signs of both dilated cardiomyopathy (DCM) and arrhythmogenic cardiomyopathy (ACM)." (PMID 37408197, 2023). "The p.Arg14del (c.40_42delAGA) phospholamban (PLN) pathogenic variant is a founder mutation that causes dilated cardiomyopathy (DCM) and arrhythmogenic cardiomyopathy (ACM)." (PMID 34143416, 2022). "Inherited cardiomyopathy caused by the p.(Arg14del) pathogenic variant of the phospholamban (PLN) gene is characterized by intracardiomyocyte PLN aggregation and can lead to severe dilated cardiomyopathy." (PMID 35269571, 2022). "The phospholamban (PLN) p.Arg14del mutation causes dilated cardiomyopathy, with the molecular disease mechanisms incompletely understood." (PMID 33998164, 2021). "Heterozygous PLN p.Arg14del mutation is associated with an arrhythmogenic dilated cardiomyopathy (DCM), whose pathogenesis has been attributed to SERCA2a “superinhibition”." (PMID 34948294, 2021). "Mutations in PLN gene, that encodes de phospholamban protein, involved in calcium signalling and muscle contraction, are associated with hypertrophic and dilated cardiomyopathy." (PMID 33530161, 2021). "The disease mechanism linking the phospholamban (PLN) p.Arg14del mutation to dilated cardiomyopathy is incompletely understood." (PMID 33998164, 2021). "R14del is a well-known PLN mutation in Dutch people, with 10–15% of both dilated cardiomyopathy and arrhythmogenic cardiomyopathy patients are claimed to be caused by PLN-R14del13." (PMID 33020536, 2020). "The first mutation described in the PLN gene was an arginine to cysteine missense mutation at residue 9 and was associated with decreased PLN phosphorylation, leading to dilated cardiomyopathy (DCM) in a large American family." (PMID 30547415, 2019). "The p.Arg14del (c.40_42delAGA) founder mutation in the PLN gene has been associated with dilated cardiomyopathy (DCM) and recently also with AC." (PMID 24732829, 2014). "The p.Arg14del mutation in the phospholamban (PLN) gene has been associated with dilated cardiomyopathy and recently also with arrhythmogenic cardiomyopathy." (PMID 24732829, 2014).